NGF (nerve growth factor)
Diseases named in the same sentence as NGF in open-access papers (continued):
Sharing a sentence is not in itself a finding about the gene and the disease.
chondrosarcoma (4 papers, 2021 to 2024). A malignant cartilaginous matrix-producing mesenchymal neoplasm arising from the bone and soft tissue. "The NGF/TrkA axis has been implicated in the metastasis of various cancers, including breast cancer 24, chondrosarcoma 25, colon cancer 26, pancreatic cancer 27, and prostate cancer." (PMID 39247831, 2024). "We also observed in that study a positive significant correlation between MMP-2 and NGF staining intensities of human chondrosarcoma tissue, indicating an association between the levels of these proteins and the progression of chondrosarcoma disease." (PMID 34815382, 2021). "Our study is the first to describe an association between NGF levels and the tumor stage in chondrosarcoma tissue specimens." (PMID 34283074, 2021). "Treatment of JJ012 cells with NGF (30, 50, or 100 ng/mL) obviously inhibited miR-149-5p synthesis in both chondrosarcoma cell lines, in a concentration-dependent manner." (PMID 34815382, 2021). "We also confirmed that NGF facilitates MMP-2-dependent chondrosarcoma cell migration and metastasis by inhibiting the miR-423-5p synthesis via FAK/c-Src signaling." (PMID 34283074, 2021). "The IHC results revealed significant increases in the levels of NGF and MMP-2 expression in the JJ012/NGF orthotopic model, confirming that NGF facilitated the metastasis of the chondrosarcoma to the mouse lung." (PMID 34283074, 2021). "We also confirmed that NGF facilitates LOX-dependent chondrosarcoma cell migration and metastasis by suppressing miR-149-5p synthesis via PI3K, Akt, and mTOR signaling." (PMID 34815382, 2021). "We suggest that NGF is a worthwhile therapeutic target in the treatment of a metastatic chondrosarcoma." (PMID 34283074, 2021). "A positive correlation observed between the MMP-2 and NGF staining intensity of the human chondrosarcoma tissue (r2 = 0.6) indicated that the levels of these proteins were associated with the progression of chondrosarcoma disease." (PMID 34283074, 2021). "We report that NGF facilitates lysyl oxidase (LOX)-dependent cellular migration and invasion in human chondrosarcoma cells, and that NGF overexpression enhances lung metastasis in a mouse model of chondrosarcoma." (PMID 34815382, 2021). "The evidence from the in vitro and in vivo results suggested that NGF facilitates the chondrosarcoma metastasis." (PMID 34283074, 2021). "Treatment of chondrosarcoma cells with NGF promoted invasion and migration ability, according to Transwell assay data." (PMID 34815382, 2021). "We first investigated the effects of NGF upon cell motility in chondrosarcoma cell lines SW1353 and JJ012." (PMID 34283074, 2021). "Our data indicate that endogenous NGF augments LOX-dependent lung metastasis of chondrosarcoma in mice." (PMID 34815382, 2021). "In conclusion, our study identified that NGF promoted the MMP-2-dependent cell migration in human chondrosarcoma tissue by inhibiting the miR-423-5p synthesis via the FAK and c-Src signaling cascades." (PMID 34283074, 2021). "The IHC tissue array results revealed higher levels of NGF and MMP-2 expression in patients with a higher grade chondrosarcoma than in those with a lower grade disease; the levels of NGF and MMP-2 expression were reflected by the tumor stage." (PMID 34283074, 2021). "NGF facilitated the MMP-2-dependent cellular migration in human chondrosarcoma JJ012 cells while the overexpression of NGF enhanced the lung metastasis in a mouse model of a chondrosarcoma." (PMID 34283074, 2021). "Stimulation of cells with NGF enhanced LOX mRNA and protein expression, implying that LOX is critical to NGF-promoted chondrosarcoma cell migration and invasion." (PMID 34815382, 2021). "Our in vitro and in vivo evidence suggests that NGF facilitates LOX-dependent chondrosarcoma metastasis." (PMID 34815382, 2021).
chondrosarcoma (continued). "A positive correlation observed between NGF and LOX staining intensity of human chondrosarcoma tissue (r2 = 0.534) indicates that the levels of these proteins (NGF and LOX) are associated with the progression of chondrosarcoma disease." (PMID 34815382, 2021). "We first investigated the effects of NGF upon cell motility in chondrosarcoma cell lines JJ012 and SW1353." (PMID 34815382, 2021). "Immunohistochemistry (IHC) results revealed significant increases in the levels of LOX expression in the JJ012/NGF orthotopic model, confirming that NGF facilitates the metastasis of chondrosarcoma to the mouse lung." (PMID 34815382, 2021). "We used the orthotopic in vivo model of chondrosarcoma lung metastasis to further investigate the promoting effects of NGF in a metastatic chondrosarcoma." (PMID 34283074, 2021). "Finally, NGF has been shown to facilitate chondrosarcoma metastasis through the activation of FAK/c-Src signaling." (PMID 39247831, 2024). "Whether TrkA inhibition antagonizes the NGF-mediated chondrosarcoma metastasis is yet to be confirmed." (PMID 34283074, 2021). "It appears to be worth targeting NGF expression in metastatic chondrosarcoma." (PMID 34815382, 2021). "We therefore examined whether the LOX family plays a role in NGF-induced migration and invasion in chondrosarcoma." (PMID 34815382, 2021). "We also sought to determine whether LOX mediates NGF-induced migration and invasion abilities of chondrosarcoma cells, and whether this process is regulated by PI3K, Akt, and mTOR signaling." (PMID 34815382, 2021). "Treatment of chondrosarcoma cell lines with NGF upregulated mTOR phosphorylation." (PMID 34815382, 2021). "The effect of NGF in a chondrosarcoma metastasis is uncertain." (PMID 34283074, 2021). "In this study, we found that NGF promotes chondrosarcoma metastasis in vitro and in vivo." (PMID 34283074, 2021). "In our previous experiments, we used an established orthotopic mouse model of chondrosarcoma lung metastasis to examine the stimulatory effects of NGF in metastatic chondrosarcoma, which confirmed that NGF promotes chondrosarcoma metastasis in mouse lungs by stimulating MMP-2 expression." (PMID 34815382, 2021). "NGF appears to be a worthwhile therapeutic target in the treatment of a metastatic chondrosarcoma." (PMID 34283074, 2021). "It appears to be worth targeting NGF expression in a metastatic chondrosarcoma." (PMID 34283074, 2021). "We therefore set out to define how NGF could affect chondrosarcoma metastasis, in in vitro and in vivo explorations." (PMID 34815382, 2021). "Here, we found that NGF promotes the chondrosarcoma migration and metastasis in vitro and in vivo." (PMID 34283074, 2021). "The treatment of JJ012 cells with NGF (100 ng/mL) significantly reduced miR-423-5p expression and at the concentrations of 30, 50 or 100 ng/mL, significantly inhibited the miR-423-5p synthesis in both chondrosarcoma cell lines in a concentration-dependent manner." (PMID 34283074, 2021). "Finally, we examined potential candidate miRNAs that could affect LOX mRNA expression in chondrosarcoma cell lines, and the potential role of NGF in this process." (PMID 34815382, 2021). "We then examined whether MMP-2 played a role in NGF-regulated migration in a chondrosarcoma." (PMID 34283074, 2021). "Thus, NGF appears to be a worthwhile therapeutic target for metastatic chondrosarcoma." (PMID 34815382, 2021). "Our study results here show that NGF promotes phosphorylation of PI3K and Akt, while PI3K and Akt pharmacological inhibitors suppress NGF-induced promotion of LOX expression, chondrosarcoma cell migration, and invasion." (PMID 34815382, 2021). "Here, we found that the levels of NGF and matrix metalloproteinase-2 (MMP-2) correlated with the tumor stage in patients with a chondrosarcoma." (PMID 34283074, 2021).
chondrosarcoma (continued). "Treating cells with a FAK inhibitor diminished the NGF-induced c-Src phosphorylation indicating that the FAK/c-Src signaling cascade regulated the NGF-induced MMP-2 synthesis and chondrosarcoma cell migration." (PMID 34283074, 2021). "The levels of NGF and MMP-2 in human chondrosarcoma tumor tissues correlated strongly with the tumor stage." (PMID 34283074, 2021). "Our investigation has found that levels of NGF and LOX expression are positively correlated with tumor staging in patients with chondrosarcoma." (PMID 34815382, 2021). "We have also previously found that the pretreatment of chondrosarcoma cells with MEK, ERK, JNK, p38, and PKCα/β inhibitors downregulated NGF-induced stimulation of cell migration (unpublished data)." (PMID 34815382, 2021). "In previous IHC tissue array investigations, we have documented higher levels of NGF and MMP-2 expression in patients with higher-grade chondrosarcoma than in those with lower-grade disease." (PMID 34815382, 2021). "Here, our results showed that NGF promoted the phosphorylation of FAK and c-Src while FAK and c-Src pharmacological inhibitors suppressed the NGF-induced promotion of MMP-2 expression and the chondrosarcoma migration." (PMID 34283074, 2021). "We identified that NGF induces the MMP-2 synthesis and chondrosarcoma cell motility by inhibiting miR-423-5p expression through the FAK and c-Src pathways." (PMID 34283074, 2021). "In conclusion, our study has identified that NGF promotes LOX-dependent migratory and invasive activities in human chondrosarcoma cells by suppressing miR-149-5p synthesis via the PI3K, Akt, and mTOR signaling cascades." (PMID 34815382, 2021). "In our previous study, NGF promoted MMP-2 expression and chondrosarcoma cell migration through the FAK and c-Src signaling cascades." (PMID 34815382, 2021). "We have previously reported that NGF promotes MMP-2 expression and chondrosarcoma cell migration by inhibiting miR-423-5p expression through the FAK and c-Src signaling cascades." (PMID 34815382, 2021). "Our investigation has found that levels of NGF and MMP-2 expression are positively correlated with the tumor staging in patients with a chondrosarcoma." (PMID 34283074, 2021). "The transfection of cells with an miR-423-5p mimic significantly reduced the NGF-induced stimulation of the cell migration and MMP-2 mRNA expression in both chondrosarcoma cell lines." (PMID 34283074, 2021). "PI3K and Akt inhibitors also inhibited NGF-promoted phosphorylation of mTOR, indicating that PI3K/Akt-dependent mTOR activation mediates NGF-facilitated promotion of LOX synthesis and chondrosarcoma cell motility." (PMID 34815382, 2021). "PI3K inhibitor treatment antagonized NGF-facilitated Akt phosphorylation, indicating that the PI3K/Akt signaling pathway controls NGF-enhanced LOX synthesis, as well as chondrosarcoma cell migration and invasion." (PMID 34815382, 2021). "The transfection of cells with MMP-2 siRNA diminished the NGF-induced promotion of migration, implying that MMP-2 was critical to NGF-induced chondrosarcoma cell migration." (PMID 34283074, 2021). "Notably, levels of NGF and LOX expression correlated with tumor stage in human chondrosarcoma samples." (PMID 34815382, 2021). "The effects of NGF in a chondrosarcoma are not confirmed although NGF is capable of promoting the progression and metastasis of several different types of tumors." (PMID 34283074, 2021). "Treating chondrosarcoma with PI3K, Akt, and mTOR inhibitors reversed NGF-promoted inhibition of miR-149-5p expression, which suggests that NGF may increase LOX expression and chondrosarcoma metastasis by inhibiting miR-149-5p synthesis via the PI3K, Akt, and mTOR signaling cascades." (PMID 34815382, 2021).
chondrosarcoma (continued). "Nerve growth factor (NGF) is critical for neuronal cell growth, apoptosis, and differentiation, and also appears to promote the progression and metastasis of several different types of tumors, although the effects of NGF upon chondrosarcoma mechanisms are not very clear." (PMID 34815382, 2021). "Nerve growth factor (NGF) is capable of promoting the progression and metastasis of several different types of tumors although the effects of NGF in a chondrosarcoma are not confirmed." (PMID 34283074, 2021).
chronic pancreatitis (4 papers, 2012 to 2024). A chronic inflammatory process causing damage and fibrosis of the pancreatic parenchyma. "And siRNA-mediated knockdown of TRPV1 diminishes spontaneous visceral pain in mice, whereas upregulation of TRPV1 expression and function by administration of the nerve growth factor (NGF) has been shown to promote pain in chronic pancreatitis." (PMID 25614752, 2014). "The chronic pancreatitis patients showed increasing NGF and Trk-A immunoreactivity." (PMID 34174790, 2021).
complex regional pain syndrome (4 papers, 2015 to 2022). A chronic pain syndrome characterized by a disproportionate spontaneous or stimulus-induced pain, accompanied by a variably mixed myriad of autonomic and motor disorders including symptoms such as swelling, allodynia, skin blood supply and trophic disturbances. "The limitation of this study is the insufficient analgesic effect on allodynia-related pathologies, such as complex regional pain syndrome after intra-articular injection of the NGF antibody, as suggested from our results." (PMID 33806315, 2021). "Some authors have focused on establishing a specific treatment for complex regional pain syndrome by studying the role of receptor tyrosine kinase for NGF in patients with CIPA." (PMID 26579324, 2015).
Dry skin (4 papers, 2015 to 2021). Skin characterized by the lack of natural or normal moisture. "NGF produced by keratinocytes is one of the major growth factors that determines skin innervations, with higher local NGF concentrations in the lesional skin of patients with AD or xerosis than in normal skin." (PMID 33905439, 2021).
gastric tumors (4 papers, 2020 to 2023). "Expression of NGF and YAP was also associated with advanced stages of gastric tumors, which further substantiates the critical roles of Chrm3-NGF and Chrm3-YAP axes in tumor pathology." (PMID 32477953, 2020). "Hayakawa et.al found that the overexpression of NGF significantly accelerated the growth and invasion of gastric tumors." (PMID 36522730, 2022).
generalized anxiety disorder (4 papers, 2012 to 2025). An anxiety disorder characterized by excessive and difficult-to-control worry about a number of life situations. "The serum levels of nerve growth factor were significantly higher in patients with generalized anxiety disorder after CBT." (PMID 39937424, 2025). "Raised serum NGF levels have been reported as an acute stress reaction and NGF serum concentrations rise after successful cognitive-behavioral therapy of generalized anxiety disorder." (PMID 23028581, 2012). "Indeed, although it was previously shown that NGF levels raise in the serum of soldiers in proximity to their first parachute jumps, in patients affected by generalized anxiety disorder (GAD), NGF levels were not different from controls." (PMID 26539329, 2015).
Hearing impairment (4 papers, 2015 to 2024). A decreased magnitude of the sensory perception of sound. "In 2015, Indian researchers reported that a twin sister had sensorineural hearing loss suggesting that the NGF-TRKA signaling pathway may be involved in the development of auditory nerves." (PMID 38241559, 2024). "Low blood NGF levels seem to be associated with sensorineural hearing loss and tinnitus." (PMID 37736859, 2023). "DM may induce hearing impairment through loss of OHCs, spiral ganglion neuron atrophy, and decreased NGF levels." (PMID 25878713, 2015). "The findings of this study show that recovery effect of DA9801 in the hearing impairment produced by DM model could be elicited by inducing NGF expression through Nr3c1 protein expression via Akt transformation." (PMID 25878713, 2015). "Interestingly, intranasal administration of NGF resulted protective in counteracting hearing impairment in SAMP8 mice, ameliorating hearing performances (analyzed by auditory brainstem responses and distortion product otoacoustic emission) and hair cells morphology (analyzed by microscopy analysis)." (PMID 37704645, 2023).
hypothyroidism (4 papers, 2018 to 2025). Abnormally low levels of thyroid hormone. "It is also possible that hypothyroidism-impaired NGF maturation results in elevated levels of TR that overcompensate and propel the cell towards survival." (PMID 32259096, 2018). "Interestingly, it has been shown that hypothyroidism not only impairs the maturation of NGF but also enhances the expression and proteolysis of the p75NTR receptor suggesting increased signalling via this receptor." (PMID 32259096, 2018). "These suggest a possible link between hypothyroidism, increased APP synthesis, and processing, as well as decreased NGF maturation and function." (PMID 32259096, 2018).
keratoconus (4 papers, 2015 to 2025). A degenerative, structural disorder of the eye, characterized by a cone-shaped protrusion of the cornea. "Their findings indicate that the tear level of IL-13, in conjunction with NGF, can reliably predict the advancement of keratoconus, boasting a specificity of 100% and a sensitivity of 80%." (PMID 38256126, 2024). "This is the largest study to date that assesses NGF levels in patients with keratoconus’ tears and the second in terms of observing changes in this parameter after CXL." (PMID 38203537, 2023). "Further research is needed on the role of NGF and other inflammatory biomarkers for rapid diagnosis and selection of targeted therapy in patients with keratoconus." (PMID 38203537, 2023). "Interesting reports by Fodor M suggest that the level of NGF, in combination with IL-13, can predict corneal keratoconus progression with 100% specificity and 80% sensitivity." (PMID 38203537, 2023). "In our study, we focused on the analysis of nerve growth factor in patients with keratoconus before CXL and observed changes in the secretion of this factor after the procedure." (PMID 38203537, 2023). "Studies of tears and corneas in patients with keratoconus have revealed altered levels of inflammatory markers, including the nerve growth factor (NGF)." (PMID 38203537, 2023). "In our study, the NGF level was significantly reduced (8.11) in the patients with keratoconus compared to the control group (16.73), p < 0.001." (PMID 38203537, 2023). "This demonstrates the significant role of the NGF in the pathophysiology of keratoconus and emphasises the importance of conducting further research to determine its potential role in disease progression." (PMID 38203537, 2023). "Using this hypothesis, it can be deduced that individuals with keratoconus undergo a downregulation of NGF secretion, which our research results may confirm." (PMID 38203537, 2023). "The Food and Drug Administration (FDA) has approved eye drops containing NGF, which hold promise in the treatment of neurotrophic keratitis and may prove to be an effective treatment in other ophthalmic conditions requiring corneal regeneration, such as keratoconus." (PMID 38203537, 2023). "It is strange that there was no significant increase in NGF secretion after CXL in patients with keratoconus." (PMID 38203537, 2023). "This study found a lack of TrkA and a significant decrease in the p75 and NGF levels in the corneas of patients with keratoconus compared to healthy subjects." (PMID 38203537, 2023). "According to A. Lambiase, the molecular basis of keratoconus is the complete absence of NGF TrkA receptor (TrkA NGFR) expression and decreased NGF and p75 NTR expression, which consequently cause the dysregulation of the NGF secretion pathway, resulting in reduced NGF secretion." (PMID 38203537, 2023).
macular degeneration (4 papers, 2023 to 2025). Loss of vision in the central portion of the retina (macula), secondary to retinal degeneration. "This body of scientific evidence has led to the hypothesis that NGF may also play a beneficial role in macular degeneration." (PMID 39056738, 2024).